PPARG (peroxisome proliferator activated receptor gamma)
Diseases named in the same sentence as PPARG in open-access papers (continued):
Sharing a sentence is not in itself a finding about the gene and the disease.
Hepatic steatosis (continued). "The hepatic overexpression of Dgat2, which catalyzes the final step of triglyceride synthesis, led to hepatic steatosis in mice, and liver-specific disruption of Pparγ or Srebf1 protected mice against hepatic steatosis." (PMID 27213439, 2016). "It has been established that the increased expression of PPARγ results in development of fatty liver, which is typical for chronic alcohol abuse." (PMID 27348013, 2016). "In Nocturnin-KO mice fed with HFD, liver PPARγ oscillation was abolished, accompanied by a reduced expression of many genes related to lipid metabolism and resistance to hepatic steatosis." (PMID 28115925, 2016). "In this study, we established that SIRT1 is involved in alcoholic hepatic steatosis by regulating the acetylation of PPARγ and its activity." (PMID 27404390, 2016). "In the present study, we observed that isorhamnetin attenuated fat droplets and improved liver morphology in DIO mice in a similar fashion to other PPARγ antagonists, suggesting that isorhamnetin can be used to prevent hepatic steatosis." (PMID 26775807, 2016). "We demonstrated that SIRT1 overexpression attenuates ethanol-induced hepatic steatosis, in which PPARγ acetylation is decreased." (PMID 27404390, 2016). "Similar to mice, inhibition of vanin activity did not affect bodyweight, food intake or hepatic steatosis as measured by TG levels, supported by similar expression of hepatic PPARγ." (PMID 26932716, 2016). "On the other hand, hepatic PPARγ, which is known as a critical regulator of TG accumulation in adipose tissue, has yet to be investigated in alcohol-induced hepatic steatosis until now." (PMID 27404390, 2016). "Nrg4 gene transfer curbed HFD-induced hepatic steatosis by inhibiting lipogenesis and PPARγ-mediated lipid storage." (PMID 27184920, 2016). "Increased expression of PPARγ was observed in mice with hepatic steatosis induced by high-fat diet (HFD)." (PMID 26246839, 2015). "Drugs like pioglitazone, a peroxisome proliferator-activated receptor gamma (PPARγ) agonist, and liraglutide, a glucagon like peptide 1 receptor agonist have been shown to reduce liver triglyceride and hepatic steatosis also through reduction of DNL." (PMID 26580649, 2015). "In contrast to these studies showing a deleterious effect of PPARγ on NAFLD, adenovirus-mediated overexpression of PPARγ in methionine-choline deficient (MCD) diet-induced models of NAFLD were shown to improve hepatic steatosis, inflammation and fibrosis." (PMID 26035752, 2015). "Overexpressing H-apoD in HepG2 cells in the presence of AA strongly suggests that the presence of hepatic steatosis in Tg mice is the result of PPARγ activation by AA, one of the main ligand of apoD." (PMID 26083030, 2015). "Peroxisome proliferator-activated receptor gamma (PPARγ) is another transcription factor involved in the development of hepatic steatosis in rodents." (PMID 25892856, 2015). "Our study describes for the first time a role for apoD in the regulation of PPARγ and the downstream activation of metabolic pathways leading to hepatic steatosis." (PMID 26083030, 2015). "On the other hand, it is widely known that the increased expression of PPARγ in the hepatic tissue in a murine model plays an important deleterious role, increasing hepatic steatosis." (PMID 25875942, 2015). "We also showed a role for PPARγ in negatively regulating eNOS expression in adipocytes, which has important therapeutic implications for the treatment of fatty liver and related disorders." (PMID 26317347, 2015). "We demonstrate that obese MIF−/− mice have reduced hepatomegaly, lower systemic ALT levels and are partially protected from HFD-induced hepatic steatosis; coincident with reduced Pparγ and Srebp-1c mRNA expression compared to WT." (PMID 25412423, 2014). "Accordingly, deletion of PPARγ in hepatocytes protects mice against high-fat diet induced hepatic steatosis." (PMID 24799887, 2014).
Hepatic steatosis (continued). "Peroxisome proliferator-activated receptor gamma (PPARγ) has been recently proposed as one of the receptors involved in the MIE for liver steatosis (the early manifestation of NAFLD)." (PMID 24772164, 2014). "In the present study, we confirmed that KKAy mice developed obvious hepatic steatosis, manifesting in massive hepatic lipid accumulation and accompanied with upregulation of the PPARγ gene as well as adipocyte-specific gene in the liver." (PMID 24799887, 2014). "Taken together, these results suggest that HBCD exposure in HFD-fed mice activates PPARγ and, possibly, lipid transport-related genes induced by PPARγ, and that these changes lead to development of hepatic steatosis." (PMID 24398136, 2014). "Nevertheless, several studies have shown that overexpression of PPARγ can prevent the progression of hepatic steatosis in mouse models and treatment with the PPARγ agonist rosiglitazone has been shown to have similar effects." (PMID 24209497, 2013). "We recently reported that TDAG51 deficiency induced age‐associated adipogenesis and hepatic steatosis in TDAG51−/− mice, further implicating PPARγ in modulating the effects of TDAG51 deficiency." (PMID 23686369, 2013). "Overall, these sets of data suggest that Pparγ ameliorated hepatic steatosis due to increased fatty acid oxidation." (PMID 22966224, 2012). "In accordance, targeted deletion of PPARγ in hepatocytes protects mice against diet-induced hepatic steatosis, suggesting a prosteatotic role of PPARγ." (PMID 22675337, 2012). "Diet induced hepatic fibrosis mouse models that were either treated with rosiglitazone or administered with adenovirus overexpressing Pparγ were shown to ameliorate hepatic steatosis." (PMID 22966224, 2012). "The genetic deletion of hepatic PPARγ protected against hepatic steatosis in high fat diet-induced obese mice." (PMID 23145054, 2012). "By contrast, different results have been reported regarding the effect of PPARγ on hepatic steatosis." (PMID 22675337, 2012). "Mice with specific inactivation of the NF-kappaB essential modulator gene (NEMO (L-KO) mice) exposed to a high-fat diet display a worsened liver steatosis as a consequence of PPARα and increased PPARγ expression." (PMID 23028383, 2012). "In hepatic steatosis, both PPARγ and GPAT1 are normally upregulated, and adenovirus-mediated overexpression of GPAT1 in rat liver promotes the development of hepatic steatosis within 5–7 days." (PMID 21533082, 2011). "It has been previously shown that PPARγ antagonizes inflammatory responses by a transrepression of NF-κB regulators and that its hepatic activation leads to the development of liver steatosis." (PMID 19680557, 2009). "In contrast, network members promoting development of hepatic steatosis, such as PPARγ, SCD, SREBF1, ACOX1, CIDEC and CFD (adipsin) are repressed during early phase and induced during the late phase of hepatic response to HF diets." (PMID 19680557, 2009). "In contrast, mice that specifically lack PPARγ in liver are protected from hepatic steatosis and show decreasedexpression levels of lipogenic genes compared to wild-type mice." (PMID 17389767, 2007). "Mechanistically, the combination of FA and MLT might alleviate hepatic ERS by activating AMPK, thereby enhancing PPARγ-mediated lipolysis of LD, ultimately reducing lipid accumulation and preventing hepatic steatosis." (PMID 41373932, 2025). "SIRT1 transgenic mice, which show reduced PPARγ acetylation, are protected from ethanol-induced hepatic steatosis, suggesting that modulating PPARγ acetylation through SIRT1 could be an effective therapeutic strategy." (PMID 40052151, 2025). "Our results suggest that liver steatosis induced by sucrose could be related with impaired calpain activity, which could promote PPARγ increase." (PMID 41468440, 2025). "Excessive activation of PPARγ can lead to fat accumulation and hepatic steatosis, while inhibition of this pathway may have antiobesity and antidiabetic effects." (PMID 40968591, 2025).
Hepatic steatosis (continued). "Hepatocyte-specific deletion of PPARγ reduces hepatic steatosis in obese mice." (PMID 41438090, 2025). "However, another study reported that targeted deletion of PPARG inhibited hepatic steatosis in NAFLD mice, while PPARG was highly expressed in NAFLD patients, suggesting its role in promoting steatosis." (PMID 40600138, 2025). "Moreover, the inactivation of liver PPARγ abolished rosiglitazone-induced an increase in hepatic TG and improved hepatic steatosis in lipoatrophic AZIP mice." (PMID 39436790, 2024). "Interestingly, the PPARG agonist Lobe mitigates hepatic steatosis and preadipocyte differentiation induced by STAT3 inactivation, highlighting the role of STAT3 in regulating lipid metabolism via PPARG." (PMID 39125712, 2024). "Lobeglitazone, another PPARγ agonist, also leads to moderate weight gain and attenuates hepatic steatosis, with an improvement of glucose and lipid homeostasis in patients with T2D; however, more randomized controlled trials must be conducted to further assess the effects of lobeglitazone." (PMID 39200340, 2024). "Secondly, folic acid exhibits potent antioxidant properties, enhancing mitochondrial β-oxidation, reducing oxidative stress, and inhibiting peroxisome proliferator-activated receptor γ (PPARγ), a key regulator of lipogenesis and hepatic TG accumulation, thereby mitigating hepatic steatosis." (PMID 39296498, 2024). "Furthermore, there is a strong correlation between the onset of hepatic steatosis and hepatocyte-specific PPARγ expression." (PMID 39436790, 2024). "These drugs activate peroxisome proliferator-activated receptor gamma (PPARγ), which enhances insulin sensitivity, reduces liver steatosis, and has anti-inflammatory effects, which may contribute to a reduced risk of HCC." (PMID 39597914, 2024). "Similarly, the study conducted in patients with non-alcoholic steatohepatitis showed that participants treated by PPARγ agonist had less hepatic steatosis and necroinflammation partly due to elevated adiponectin levels." (PMID 38886355, 2024). "atRA has also been reported to reduce hepatic lipid accumulation in liver steatosis model animals by repressing peroxisome proliferator-activated receptor gamma (PPARγ) and to induce lipolysis by a PPARβ/δ-mediated increase in the levels of hormone-sensitive lipase (HSL) in adipocytes." (PMID 39032560, 2024). "The master regulator of adipogenesis, PPARγ gene expression, was found to be upregulated in the compound-treated adipocytes but downregulated in the hepatocytes, showing the contribution to the regulation of hepatic steatosis." (PMID 39759127, 2024). "Additionally, an overexpression of PPARγ can result in liver steatosis, a condition that can be mitigated through the administration of GW9662." (PMID 38276299, 2024). "Moreover, administration of PPARγ antagonist T0070907 mitigated the hepatic Cd36 and Cidea/c increase and improved Snhg3-induced hepatic steatosis." (PMID 39436790, 2024). "Collectively, these results suggested that PPARγ-mediated Snhg3-induced hepatic steatosis." (PMID 39436790, 2024). "The administration of PPARγ antagonist T0070907 improved Snhg3-aggravated hepatic steatosis." (PMID 39436790, 2024). "In addition, hepatocyte-specific Pparγ deletion improves hepatic steatosis by attenuating the expression of the de novo lipogenesis genes (FAS, ACC, and SCD1)." (PMID 39200340, 2024). "Increased expression of PPARγ has been observed in patients with fatty liver disease." (PMID 39268531, 2024). "Therefore, high fat diet-associated peroxisome proliferator-activated receptor-gamma (PPAR-γ) enhances and develops fatty liver." (PMID 36769165, 2023). "It has been shown that a partial activator of PPARγ, telmisaten, in combination with activating PPARα in the liver, could alleviate hepatic steatosis in mice that were fed a high-fat diet." (PMID 37096195, 2023).
Hepatic steatosis (continued). "Here, myeloid-FATP4 deficiency may promote male-prone abnormalities by exacerbating hepatic steatosis possibly via the strong activation of PPARγ, CEBPα, and p-FoxO1 in their Kupffer cells." (PMID 36881564, 2023). "However, adverse effects were found in this lineage, including increased hepatic steatosis and adipocyte hypertrophy, highlighting that in all conditions decreased PPARγ expression was observed." (PMID 37189379, 2023). "PPARγ deficiency in rodents leads to hepatic steatosis and lipodystrophy, since there is no other component to replace the role of PPARγ in adipogenesis." (PMID 36986146, 2023). "PPARγ is proved to be closely associated with hepatic lipid metabolism and play important roles in NAFLD The hepatic PPARγ plays a role in the development of fatty liver in the NAFLD patients." (PMID 36675107, 2023). "While PPARγ level was elevated in the liver of obese mice, TRF effectively reduced PPARγ and the associated lipogenic gene expression, along with a reduction in fatty liver disease." (PMID 37299580, 2023). "Accumulating evidence supported that nuclear transcription factors such as peroxisome proliferator-activated receptors γ (PPARγ) and lipid droplet-associated protein adipose differentiation-related protein (ADRP) play important roles in the development of fatty liver." (PMID 35432557, 2022). "Liver-specific deletion of PPARγ improves hepatic steatosis." (PMID 35745205, 2022). "In addition, at the molecular level, we detected significantly changed expression of the Pparγ (downregulation) and Il-6 (upregulation) genes, both of which are involved in the regulation of lipid metabolism and the pathogenesis of hepatic steatosis." (PMID 36013467, 2022). "CD36 is a transcriptional target of PPARγ in promoting hepatic steatosis." (PMID 35682942, 2022). "Many studies have demonstrated a link between elevated PPARγ expression and hepatic steatosis." (PMID 36359869, 2022). "S6B), undermining PPARγ contribution during liver steatosis." (PMID 35333579, 2022). "An early study has identified that RARα overexpression alleviated hepatic steatosis via suppressing HNF4α-regulated PPARγ expression, but whether CD36 is involved in RARα’s regulation on hepatic lipid metabolism is unknown." (PMID 35745142, 2022). "However, clinical trials suggest that the PPARγ agonists rosiglitazone and pioglitazone significantly reduce hepatic steatosis in NAFLD patients." (PMID 36552725, 2022). "Similarly, PPARγ plays an important role in the mitochondrial stress response, being activated by fatty acids and exhibiting high expression in fatty liver disease." (PMID 35087037, 2022). "Furthermore, 5-CQA induces the activity of antioxidant, and scavenges reactive oxygen species (ROS), which suppresses the expression of inflammation and the inhibition of PPARγ, and then prevents and improves liver steatosis." (PMID 34884968, 2021). "Among the identified TFs, PPARγ could emerge as a therapeutic target for fatty liver in WD, especially during the course of treatment with PCA or other copper chelators." (PMID 34098115, 2021). "The effects of PPARγ agonism on the liver remain under debate, with some studies showing that it promotes hepatic steatosis through upregulation of the genes involved in lipid uptake and storage and other studies showing that it prevents hepatic steatosis and fibrosis." (PMID 33510287, 2021). "PPARγ has significant functions also in the liver: in hepatocytes, PPARγ promotes cellular uptake of free fatty acids and induces de novo lipogenesis thereby aggravating liver steatosis, whereas in Kupffer cells and in hepatic stellate cells PPARγ activation seems to be beneficial." (PMID 34835949, 2021). "In this study, we found that Djulis hull crude extract could activate PPARγ to reduce inflammatory factors and hepatic lipid accumulation, indicating that Djulis hull crude extract could activate PPARγ to improve hepatic steatosis in HFD-fed mice." (PMID 34829565, 2021).
Hepatic steatosis (continued). "However, perilipin proteins are expressed in liver steatosis, and PLIN4 has been associated with increased PPARγ expression and hepatic lipid accumulation." (PMID 34835949, 2021). "Here, we concluded that chronic Western diet-composition administered for 20 weeks may surpass the non-alcoholic fatty liver (NAFL) stage but may be at an intermediate stage between fatty liver and fibrosis via miR-27b-5p-induced PPARγ downregulation." (PMID 33673073, 2021). "Thus, this study demonstrated that auranofin decreased hepatic steatosis by inhibiting PPARγ, which plays a key role in lipid storage and synthesis." (PMID 33114221, 2020). "A human study suggested that PPARγ might promote hepatic steatosis through the up-regulation of the SREBP-1c gene." (PMID 33383845, 2020). "Deletion of PPARγ in hepatocytes and macrophages prevent mice from developing hepatic steatosis." (PMID 32272794, 2020). "Additionally, the activation of PPARγ ameliorates hepatic steatosis by increasing serum adiponectin and upregulating the gene expression related to the β-oxidation pathway." (PMID 32443556, 2020). "Thus, PPARγ is an important upstream regulator increasing the incidence of diabetes and fatty liver disease." (PMID 32272794, 2020). "In the present study, we investigated hepatic steatosis in relation to hyperglycemia in the context of aging, as well as FoxO1 interaction with PPARγ during ER stress, in both the liver and AC2F cells, to achieve a better understanding of the molecular mechanisms involved in hepatic lipogenesis." (PMID 31246177, 2019). "Moreover, several studies have shown that PPARγ activation can prevent the progression of hepatic steatosis in murine models, and that treatment with the PPARγ agonist rosiglitazone exerts similar effects." (PMID 31930115, 2019). "In addition, the interaction between FoxO1 and PPARγ was shown to induce hepatic steatosis in aging and db/db mice." (PMID 31235676, 2019). "Expression of DGAT2 gene is involved in TG synthesis; meanwhile, it has been reported that PPARγ might be involved in HFD-induced liver steatosis." (PMID 31019978, 2019). "This suggests that NAOs may ameliorate the abnormal lipid metabolism through modulation of PPARγ expression, which might keep the mice away from fatty liver disease." (PMID 31547097, 2019). "It is still unclear whether the hepatic PPARγ activation by TZD is main mechanism to directly improve hepatic steatosis." (PMID 30008738, 2018). "Many studies showed that rosiglitazone and pioglitazone significantly improved hepatic steatosis, and this effect of these drugs is largely explained by the secondary effect of improving the insulin sensitivity of adipose tissue, where PPARγ level is mainly high." (PMID 30008738, 2018). "In addition, a recent study reported that lobeglitazone attenuated hepatic steatosis through the inhibition of PPARγ phosphorylation in chronic obese mice; however, underlying mechanism of the effects of lobeglitazone in NAFLD is still unclear." (PMID 30298052, 2018). "Because of the opposite actions of PPARα and PPARγ on hepatic steatosis, the “spillover” effects of these PPAR agonists might prevent a net gain in their ability to reduce TG accumulation in the liver." (PMID 30566427, 2018). "On the other hand, PPARγ is a nutrition-induced factor in both adipogenesis and hepatic steatosis." (PMID 29743883, 2018). "PPARγ, activated as PPARγ-retinoid x receptor functional heterodimer, contributes to FFAs uptake and hepatic steatosis through PPARγ-responsive genes, such as lipoprotein lipase (LPL), fatty acid translocase, fatty acid transport proteins and adipocyte protein 2 (aP2)." (PMID 28081181, 2017). "Our results demonstrated that pioglitazone attenuating the hepatic steatosis may be mediated by enhancing cytosolic lipolysis, β-oxidation and autophagy in a PPARα and PPARγ dependent manner." (PMID 28831172, 2017).